FBXW2 (F-box and WD repeat domain containing 2)
Diseases named in the same sentence as FBXW2 in open-access papers (continued):
Sharing a sentence is not in itself a finding about the gene and the disease.
atherosclerosis (3 papers, 2020 to 2024). A disease characterized by the build-up of fatty material and calcium deposition in the arterial wall resulting in partial or complete occlusion of the arterial lumen. "Myeloid‐specific FBXW2 gene deficiency improves both obesity‐associated with insulin resistance and atherosclerosis in murine models." (PMID 33101872, 2020). "Consistently, myeloid cell‐specific ablation of FBXW2 mitigates atherosclerosis in mice, accompanied by reduced expression of pro‐inflammatory factors in atherosclerotic lesions." (PMID 38778460, 2024). "In this study, we investigated the role of FBXW2 in metabolic chronic inflammation, including obesity and atherosclerosis." (PMID 33101872, 2020). "Using two murine models of metabolic diseases, we found that FBXW2 in macrophages is an important inflammatory regulator in the progression of obesity‐related insulin resistance and atherosclerosis." (PMID 33101872, 2020). "This work demonstrates the essential role of myeloid E3 ubiquitin ligase F‐box/WD Repeat‐Containing Protein 2 (FBXW2) in obesity‐related insulin resistance and atherosclerosis." (PMID 33101872, 2020). "We demonstrated here that FBXW2 deficiency in macrophages counteracts the detrimental effects of HFD/WD on body weight, inflammation of adipose tissue, systemic insulin insensitivity and atherosclerosis." (PMID 33101872, 2020). "Taken together, these results strongly demonstrate that FBXW2 (P3) attenuates insulin resistance and inflammation in obesity and atherosclerosis, and could serve as a potential therapeutic strategy to treat metabolic diseases." (PMID 33101872, 2020). "ApoE−/−FBXW2fl/flLysmCre+/− mice exhibited smaller lesions with fewer CD68+ plaque areas, suggesting that FBXW2 deletion in macrophages may alleviate progression of atherosclerosis in mice." (PMID 33101872, 2020). "We further discovered that FBXW2 (P3), the C‐terminal WD40 repeat domains of FBXW2, blocks the SCFFbxw2‐KSRP association and KSRP degradation, thus in turn, retarding the progress of obesity and atherosclerosis." (PMID 33101872, 2020). "In conclusion, our study identified FBXW2 as a negative regulator of KSRP, which drives the mRNA instability of proinflammatory genes and leads to inflammatory responses in macrophages during obesity‐associated insulin resistance and atherosclerosis." (PMID 33101872, 2020). "Inhibition of FBXW2 might serve as a potential approach to treating atherosclerosis." (PMID 37244925, 2023). "Furthermore, FBXW2 (P3) attenuated FBXW2‐induced KSRP ubiquitination and ameliorated HFD‐induced obesity and atherosclerosis." (PMID 33101872, 2020). "Because FBXW2 (P3) acted as an inhibitor of KSRP ubiquitination and exhibited potent protective effects against LPS‐induced inflammation in vitro, we next investigated the therapeutic effects of this segment in murine models of HFD/WD‐induced obesity and atherosclerosis." (PMID 33101872, 2020).
gastric cancer (2 papers, 2025). A primary or metastatic malignant neoplasm involving the stomach. "In this study, we employ ubiquitination and immunoprecipitation assays to demonstrate that FBXW2 acts as a substrate recognition receptor for β-catenin, inhibiting the progression of gastric cancer." (PMID 40225854, 2025). "Overall, our study demonstrates that FBXW2 inhibits gastric cancer progression by promoting β-catenin ubiquitination, highlighting its potential as a therapeutic target." (PMID 40225854, 2025). "In the withinstats plot, down-regulated FBXW2 expression was also revealed in gastric cancer specimens compared with paired adjacent samples." (PMID 40225854, 2025). "All of these indicated that down-regulated FBXW2 was correlated with the survival of gastric cancer." (PMID 40225854, 2025). "Collectively, these findings suggest that FBXW2 suppresses gastric cancer progression by facilitating β-catenin ubiquitination." (PMID 40225854, 2025). "In this study, we further demonstrate that FBXW2 promotes β-catenin ubiquitination and degradation, thereby suppressing gastric cancer growth and invasion." (PMID 40225854, 2025). "Knockdown of FBXW2 (sh-FBXW2) promoted gastric cancer cell viability and invasion while increasing β-catenin expression and reducing GSK3β and Axin2 levels." (PMID 40225854, 2025). "Down-regulated FBXW2 protein was observed in gastric cancer tissues compared with paired adjacent samples." (PMID 40225854, 2025). "In this study, we confirmed that FBXW2 plays a crucial role in regulating cell viability and invasion in gastric cancer." (PMID 40225854, 2025). "ROC analysis demonstrated that the relative expression of FBXW2 could be utilized to predict the occurrence of gastric cancer (sensitivity, 75.68%; specificity, 74.32%; AUC=0.82, P<0.001)." (PMID 40225854, 2025). "However, the potential role of FBXW2-mediated ubiquitination in gastric cancer migration and invasion remains largely unexplored." (PMID 40225854, 2025). "However, the specific binding sequence of FBXW2 with β-catenin in gastric cancer remains unclear and requires further investigation." (PMID 40225854, 2025). "Additionally, clinical samples reveal a negative correlation between FBXW2 and β-catenin expression, with FBXW2 inhibition promoting gastric cancer cell viability, colony formation, and invasion." (PMID 40225854, 2025).
endometriosis (1 paper, 2025). The growth of functional endometrial tissue in anatomic sites outside the uterine body. "This study employed an integrated multi-omics approach to identify and validate five core molecules (SRPRB, RBM3, INSIG2, GYG1, and FBXW2) demonstrating significant differential expression in both endometriosis and RIF, with robust diagnostic discriminatory power." (PMID 41462508, 2025). "Western blot analysis consistently demonstrated that the protein expression levels of SRPRB, RBM3, INSIG2, GYG1, and FBXW2 were significantly reduced in both endometriosis and RIF groups compared to the normal group, with statistical analysis validating these findings." (PMID 41462508, 2025).
gastric adenocarcinoma (1 paper, 2025). "Immunohistochemical results using the HPA database confirmed reduced FBXW2 protein levels in gastric adenocarcinoma tissues." (PMID 40721413, 2025). "RNA-seq data from the TNMplot database demonstrated that FBXW2 mRNA expression was downregulated in gastric adenocarcinoma tissues compared with normal controls, prompting us to explore whether transcriptional regulation mechanisms modulated the levels of FBXW2 mRNA." (PMID 40721413, 2025). "RNA-seq data from the TNMplot database revealed significantly lower FBXW2 expression in gastric adenocarcinoma tissues compared to normal tissues." (PMID 40721413, 2025).
Hyperglycemia (1 paper, 2020). An increased concentration of glucose in the blood. "Our data showed that FBXW2 deficiency alleviated HFD‐induced hyperglycemia and related hyperinsulinemia." (PMID 33101872, 2020).
Lung squamous cell carcinoma (1 paper, 2022). "FBXW2 was more expressed in various cancers including CHOL, COAD, neck squamous cell carcinoma (HNSC), KICH, LIHC, PRAD, and STAD.Meanwhile, lower expression was found in KIRC, LUAD, Lung squamous cell carcinoma (LUSC), THCA, and UCEC." (PMID 36591289, 2022).
Obesity (1 paper, 2020). Accumulation of substantial excess body fat. "Furthermore, it is demonstrated that the C‐terminus (P3) of FBXW2 competitively ablates the function of FBXW2 in KSRP degradation and serves as an effective inhibitor of obesity and atherogenesis progression." (PMID 33101872, 2020).
pilocytic astrocytoma (1 paper, 2025). Pilocytic astrocytoma is a rare subtype of low-grade glioma of the central nervous system characterized by a well circumscribed, often cystic, brain tumor with a discrete mural nodule and long, hair-like projections that extend from the neoplastic astrocytes.
prostatic hyperplasia (1 paper, 2022). "We found that both mRNA and protein of FBXW2 were significantly down-regulated in metastatic PCa (M-PCa) tissues than non-metastatic PCa (PCa) and prostatic hyperplasia (Con)." (PMID 35499593, 2022).
cancer (12 papers, 2017 to 2025). A tumor composed of atypical neoplastic, often pleomorphic cells that invade other tissues. "Functional characterization via gain- and loss-of-function strategies revealed that FBXW2 overexpression potently inhibited proliferation, cancer stem cell phenotype, migratory capacity, and invasive potential in human GC cell lines." (PMID 40721413, 2025). "FBXW2 has been reported to reduce expression of several proteins associated with malignant tumor states, such as β-catenin, SKP2, NF-κB p65 and EGFR, which contribute to cancer stemness, tumorigenesis and metastasis." (PMID 40721413, 2025). "Thus, FBXW2 mutations found in human cancer can be either a loss-of-function or a gain-of-function mutation." (PMID 28090088, 2017). "To further determine whether FBXW2 is inactivated via mutations in human cancers, we searched the TCGA and COSMIC databases and found that FBXW2 is indeed mutated in various human cancers." (PMID 28090088, 2017). "Finally, the gain- and loss-of-function mutations of FBXW2 are found in various human cancers." (PMID 28090088, 2017). "F-Box and WD repeat domain containing 2 (FBXW2) is an E3 ligase that inhibits cancer migration, invasion, and metastasis by promoting the degradation of oncogenic proteins, such as S-phase kinase associated protein 2 (SKP2) and β-catenin." (PMID 40299435, 2025). "Overall, FBXW2 functions as a tumor suppressor in several cancers by targeting key oncogenic proteins for degradation, thereby inhibiting tumor growth and metastasis." (PMID 40225854, 2025). "Real-time PCR and western blotting analyses revealed that the levels of FBXW2 mRNA and protein in all cancer cell lines were significantly lower than those in GES-1 cells." (PMID 40721413, 2025). "FBXW2 was more expressed in various cancers including stomach adenocarcinoma, prostate adenocarcinoma, liver hepatocellular carcinoma, kidney chromophobe, neck squamous cell carcinoma, colon adenocarcinoma and cholangiocarcinoma." (PMID 40225854, 2025). "While mining the literature for these interactomes, we discovered that several interactomes of FBXW2 act as oncogene in various cancers." (PMID 37736741, 2023). "It has been reported to be a cell-active ubiquitination inhibitor in prostate cancer that selectively degrades Skp2 and upregulates FBXW2 expression, thus inducing autophagy and inhibiting cancer cell growth." (PMID 37089937, 2023). "Previous studies showed that FBXW2 functions as putative tumor suppressor in many cancers through directing proteasomal degradation of several oncogenes including SKP2, β-catenin, and EGFR." (PMID 37736741, 2023). "Then, we also summarized previous reports on the function of the FBXW family in multiple cancers, and found that FBXW1/5 act as oncogenes in many cancers, however, FBXW2/7 exert the antitumor properties." (PMID 36591289, 2022). "Whereas the abnormal expression of FBXW2 was related to twelve different cancers, seven of which were upregulated and five were down-regulated." (PMID 36591289, 2022). "Identification of SKP2 as a novel substrate of FBXW2 extended the list of FBXW2 substrates and revealed its biological function in human cancer." (PMID 28090088, 2017). "More extensive studies are required to elucidate the contribution of FBXW2 in cancer stemness." (PMID 40721413, 2025). "Further, we performed long-term colony formation assay to assess whether FBXW2 controls cancer cell proliferation through monitoring expression levels of Moesin." (PMID 37736741, 2023). "We then speculated that SKP2 might also protect Moesin from proteasomal degradation by FBXW2 to facilitate cancer progression." (PMID 37736741, 2023). "In future, it would be interesting to understand the molecular pathways involved in attenuation of FBXW2 in cancer, which could be explored to restore the expression levels of FBXW2 to limit the Moesin expression levels." (PMID 37736741, 2023).
cancer (continued). "Target genes of miR-576 (CUL3 and RAC1) have been identified to be involved in the regulation of multiple cancer-related biological pathways, and the target genes of miR-616 (ASB13 and FBXW2) have been reported to be associated with the development of other cancers." (PMID 35008363, 2021). "Biological function of FBXW2 in any given human cancer is totally unknown." (PMID 28090088, 2017). "Collectively, this study establishes FBXW2 as a critical tumor suppressor in GC, operating through ubiquitin-mediated degradation of WASL to inhibit cancer progression." (PMID 40721413, 2025). "E3 ligases F-Box and WD repeat domain containing 2 (FBXW2), FBW7, Ub-protein ligase E3C (UBE3C), and F-Box protein 22 (FBXO22) play vital roles in cancer metastasis." (PMID 39048965, 2024). "For instance, FBXW2 functions as a tumor suppressor by facilitating the ubiquitination and degradation of oncogenic proteins such as SKP2 and β-catenin, thus impeding cancer migration, invasion, and metastasis." (PMID 39048965, 2024). "Besides, β-TrCP1 promotes another F-box protein FBXW2 ubiquitination, and so does FBXW2 to SKP2, then the β-TrCP1-FBXW2-SKP2 axis presents an oncogene-tumor suppressor-oncogene cascade that controls cancer cell growth." (PMID 32226545, 2020).
tumor (10 papers, 2017 to 2025). "As a critical E3 ubiquitin ligase, FBXW2 retards tumor proliferation and metastasis via degrading tumor-associated transcription factors or coactivators." (PMID 35614517, 2022). "Immunohistochemical analysis showed that FBXW2 overexpression enhanced FBXW2 immunoreactivity while suppressing the expression of cell proliferation marker Ki67 in tumor tissues." (PMID 40721413, 2025). "Next, xenograft tumor formation in nude mice was analyzed to determine the contribution of FBXW2 to GC cell-derived tumorigenesis." (PMID 40721413, 2025). "Through comprehensive functional genetic manipulation approaches in both in vitro (human GC cell lines) and in vivo (cell-derived tumor xenograft mouse models) systems, we systematically investigated the tumor-suppressive effects of FBXW2." (PMID 40721413, 2025). "Gain- and loss-of-function experiments uncover that FBXW2 overexpression suppresses proliferation, stemness, migratory capacity, and invasive potential in human GC cells and tumor xenografts, while silencing of FBXW2 yield the opposite results." (PMID 40721413, 2025). "Consistently, xenograft tumor models showed that FBXW2 overexpression delayed tumor growth and suppresses pulmonary metastasis." (PMID 40721413, 2025). "Down-regulated FBXW2 expression and up-regulated β-catenin expression were detected in tumor samples compared with paired adjacent normal samples." (PMID 40225854, 2025). "Immunoblotting and IHC analysis of respective tumor samples showed efficient stabilization of Moesin upon depletion of FBXW2." (PMID 37736741, 2023). "Our study further identified that the tumor suppressing function of FBXW2 was through its ubiquitylation and degradation of EGFR and hence targeting EGFR in PCa will be a good therapeutic strategy." (PMID 35499593, 2022). "Herein, we reported that the tumor suppressor FBXW2 is an ubiquitin ligase responsible for β-catenin degradation following EGF stimulation." (PMID 30918250, 2019). "Collectively, our data show that the β-TrCP-FBXW2-SKP2 axis forms an oncogene-tumour suppressor-oncogene cascade to control cancer cell growth with FBXW2 acting as a tumour suppressor by promoting SKP2 degradation." (PMID 28090088, 2017). "To determine whether WASL was required for FBXW2-mediated tumor-suppressing effects, we synthesized WASL-overexpressing plasmid to upregulation WASL expression." (PMID 40721413, 2025). "F-box and WD repeat domain-containing protein 2 (FBXW2), a substrate receptor of the SKP1-Cullin 1-F-box (SCF) E3 ubiquitin ligase complex, has been implicated in tumor suppression across multiple malignancies; however, its role in GC progression remains undefined." (PMID 40721413, 2025). "Emerging evidence indicates that FBXW2 acts as a tumor suppressor in multiple malignancies." (PMID 40721413, 2025). "In summary, this study identifies FBXW2 as an essential regulator of malignant GC by suppressing tumor stemness, tumorigenesis and metastasis, which may be at least partially attributed to its targeting of WASL." (PMID 40721413, 2025). "In addition, High FBXW2 expression induced by Dox significantly decreased tumor sphere formation ability." (PMID 40721413, 2025). "Furthermore, Dox-induced lentiviral gene interference system reveals that silencing of FBXW2 promotes tumor growth under Dox (+) condition." (PMID 40721413, 2025). "We identified tumor suppressor FBXW2 as the first bonafide E3 ligase for Moesin." (PMID 37736741, 2023). "Collectively, the results indicated overexpression of FBXW2 could inhibit tumor growth of PCa and attenuate osteolytic bone destruction." (PMID 35499593, 2022). "Likewise, H&E staining also demonstrated that overexpression of FBXW2 dramatically reduced the tumor burden in bone." (PMID 35499593, 2022). "Taken together, these results strongly suggested that FBXW2 may as a tumor suppressor to suppress growth and metastasis of PCa cells." (PMID 35499593, 2022).
tumor (continued). "Based on that, we speculate if FBXW2 represses tumor growth and metastasis of PCa through regulating EGFR." (PMID 35499593, 2022). "Hence, we have found that FBXW2 is a tumor suppressor of PCa, which down-regulates EGFR downstream by promoting EGFR ubiquitination and degradation, resulting in repression of PCa cell proliferation and metastasis." (PMID 35499593, 2022). "Notably, FBXW2 has been identified as a tumor suppressor in multiple cancers 17-19." (PMID 40225854, 2025). "Therefore, artificial obvious changes in the expression level of FBXW2 in the tumor microenvironment may lead to different prognosis compared with the database analysis." (PMID 36591289, 2022). "Besides the newly-identified EGFR, the tumor growth and metastasis suppression effects of FBXW2 in PCa might be induced through other potential substrates of FBXW2, like SKP2." (PMID 35499593, 2022). "Whether and how FBXW2 regulates tumor invasion and metastasis is previously unknown." (PMID 30918250, 2019). "All the data shown so far strongly suggest that FBXW2 could be a tumour suppressor." (PMID 28090088, 2017). "Mechanistic insight shows that Moesin prevents FBXW2-SKP2 interaction and attenuates FBXW2-mediated SKP2 polyubiquitination and degradation ultimately leading to tumor growth." (PMID 37736741, 2023). "With Dox induction, FBXW2 overexpression led to slower tumor growth and smaller tumor volume in comparison to that without Dox." (PMID 40721413, 2025). "Using the KRAS mutant GC cell line (AGS) and the KRAS wild-type GC cell line (MKN-45), our data reveal that overexpression of FBXW2 exerts a tumor-suppressing role in both GC cell lines regardless of KRAS mutational status." (PMID 40721413, 2025). "We found that β-TrCP1 and SKP2 mRNA levels were always higher (e and data not shown), whereas FBXW2 mRNA levels were lower in tumours than that in normal tissues (and data now shown)." (PMID 28090088, 2017).
infection (3 papers, 2017 to 2022). The state of being infected such as from the introduction of a foreign agent such as serum, vaccine, antigenic substance or organism. "From three RNA interference of FBXW2 (#970, #1014 and #1174), we confirmed si-FBXW2-#1014 was the most efficient infection fragment." (PMID 35499593, 2022).